ZNF749 (zinc finger protein 749)
Description:
May be involved in transcriptional regulation.
Synonyms: FLJ16360
Tractability: PROTAC: UniProt records ubiquitination sites on it; ubiquitination databases record sites on it.
Gene: Protein-coding gene on chromosome 19 (57,435,325 to 57,447,101, forward strand). Ensembl gene ENSG00000186230.
Subcellular location: Nucleus
Subcellular location (Human Protein Atlas): Nuclear membrane; Nucleoplasm
Pathways (Reactome):
Gene expression (Transcription): Generic Transcription Pathway
Gene Ontology:
Molecular function: DNA-binding transcription factor activity, RNA polymerase II-specific; RNA polymerase II transcription regulatory region sequence-specific DNA binding
Biological process: regulation of transcription by RNA polymerase II; regulation of DNA-templated transcription
Cellular component: nucleus
Genetic constraint (gnomAD): Loss-of-function variants: 8 observed, 7.16 expected, observed/expected ratio (o/e) 1.12, 90% interval 0.65 to 1.81. That is too few expected variants to judge how well the gene tolerates losing a copy. Missense variants: 898 observed, 981.25 expected, observed/expected ratio (o/e) 0.92, 90% interval 0.87 to 0.97. Synonymous variants: 310 observed, 339.24 expected, observed/expected ratio (o/e) 0.91, 90% interval 0.83 to 1.
Homologues: Orthologues: chimpanzee ZNF749 (96% identical), macaque ZNF749 (82% identical), mouse Zfp78 (25% identical), Drosophila melanogaster CG3281 (17% identical), Drosophila melanogaster Phs (15% identical), Drosophila melanogaster CG2712 (14% identical). Paralogues in human: ZFP37 (27% identical), ZFP90 (27% identical), ZNF264 (27% identical), ZNF778 (27% identical), ZNF404 (27% identical), ZNF805 (27% identical), ZNF674 (26% identical), ZNF266 (26% identical), ZNF599 (26% identical), ZNF614 (26% identical), ZNF25 (26% identical), ZNF555 (26% identical), and 50 more.
Diseases named in the same sentence as ZNF749 in open-access papers:
ZNF749 is named in the same sentence as 3 diseases in open-access papers, as found by Europe PMC text mining. Sharing a sentence is not in itself a finding about the gene and the disease. The quoted sentences say what the papers report.
infertile (1 paper, 2024). "All OA-fertile men (n = 9) carried mutations in ZNF749 (sperm production), whereas OA-infertile men (n = 10) harbored mutations in PRB1, which is essential for DNA replication." (PMID 38403804, 2024).
ZNF749 also shares sentences with these, for which no sentence is quoted: inflammatory polyarthropathies (1 paper); rheumatoid arthritis (1).